METTL3 (methyltransferase 3, N6-adenosine-methyltransferase complex catalytic subunit)
Diseases named in the same sentence as METTL3 in open-access papers (continued):
Sharing a sentence is not in itself a finding about the gene and the disease.
glioma (continued). "Taken together, these results indicated that IGF2BP2, KIAA1429, METTL16, and METTL3, as well as 208 targets are involved in the occurrence of glioma, GBM, and LGG." (PMID 34589481, 2021). "METTL3, served as a methyltransferase, has been reported to be essential for glioma stem-like cell maintenance and radio-resistance." (PMID 32211315, 2020). "Early research indicated that short hairpin RNA (shRNA) mediated silencing of METTL3 in several glioma cell lines, both in vitro as well as in in vivo orthotopic models, resulted in enhanced GBM growth." (PMID 32375856, 2020). "In contrast, increased expression of METTL3 and METTL14 has also been implicated in glioma resistance and progression." (PMID 32296573, 2020). "Among the regulators, METTL3 has been discovered to regulate cell proliferation, tumor growth, self-renewal, and development in glioma." (PMID 33134160, 2020). "Recently, it has been shown that METTL3‐mediated m6A marks contribute to high expression of lncRNAs in glioma stem‐like cells." (PMID 32216017, 2020). "In glioma, overexpression of METTL3 is involved in glioma stem-like cell maintenance and radioresistance." (PMID 32111216, 2020). "m6A and METTL3 were found to be elevated in glioma stem-like cells in response to IR, and silencing of METTL3 reduced DSB repair and enhanced the sensitivity to IR in these cells." (PMID 32618336, 2020). "Despite recent advances in N6-methyladenosine (m6A) biology, the regulation of crucial RNA processing steps by the RNA methyltransferase-like 3 (METTL3) in glioma stem-like cells (GSCs) remains obscure." (PMID 30781903, 2019). "Collectively, from these findings, we conclude that the METTL3 enhances the activity of the Notch pathway in glioma." (PMID 30781903, 2019). "Next, we demonstrated that transcript levels of NOTCH pathway members NOTCH1, NOTCH4, DLL1 and HES-1, which carry METTL3-dependent m6A peaks, were downregulated in METTL3-silenced glioma cells." (PMID 30781903, 2019). "In accordance with our previous report, we found glioma stem cell-specific genes were downregulated post-METTL3 inhibition." (PMID 30781903, 2019). "Exogenous overexpression of a SOX2 mutant without the 3′UTR reversed the inhibitory effect of neurosphere formation in METTL3-knockdown glioma stem-like cells." (PMID 31921660, 2019). "METTL3 expression was found to be elevated in glioma stem-like cells and attenuated during differentiation." (PMID 31921660, 2019). "One recent study demonstrated a vital role of METTL3-regulated m6A modification in the maintenance and radioresistance of glioma stem-like cells." (PMID 30149601, 2018). "METTL3 was upregulated in glioma stem-like cells over the matched differentiated glioma cells and its silencing suppressed tumor growth in vivo." (PMID 30149601, 2018). "We also found that SOX2, a glioma reprogramming factor, as the METTL3 target in promoting glioma stem cell growth." (PMID 29460395, 2018). "Towards identifying the target of METTL3 in promoting glioma stem cell growth, we carried out an integrated RIP‐sequencing and RNA‐sequencing of METTL3‐silenced GSCs." (PMID 29460395, 2018). "This suggests a potential correlation between METTL3 expression and glioma malignancy." (PMID 41321637, 2025). "Another study reported that METTL3 expression is decreased in the U251 glioma cell line." (PMID 40469294, 2025). "Notably, EIF3J-AS1 knockdown in METTL3-overexpressing glioma cells significantly rescued MIF expression." (PMID 41390674, 2025). "However, the specific mechanism by which METTL3 participates in the regulation of glioma remains to be further elucidated." (PMID 41321637, 2025).
glioma (continued). "When loaded into EVs secreted by human bone marrow stromal cells (hBMSCs), miR-1208 crosses the BBB, acting as a tumor suppressor by inhibiting key pathways involved in glioma progression, by negatively regulating the expression of Methyltransferase-like 3 (METTL3) and suppressing the TGF-β pathway." (PMID 41465256, 2025). "METTL3 contributes to radioresistance in GBM by enhancing glioma stem cell (GSC) generation." (PMID 40823093, 2025). "Overexpression of miR-101 in glioma cells significantly suppressed METTL3 expression." (PMID 41390674, 2025). "In addition to participating in the proliferation and growth of gliomas, METTL3 is involved in the formation of the glioma vasculature." (PMID 40469294, 2025). "In most reported cases, METTL3 promotes the occurrence of gliomas." (PMID 40469294, 2025). "This action of YTHDF2 is dependent on METTL3-mediated m6A in gliomas." (PMID 38398118, 2024). "In addition, METTL3 silencing in GSC cells METTL3 resulted in reduced expression of glioma reprogramming factors, including SOX2 (SRY-box 2)." (PMID 38398118, 2024). "The expression of METTL3 shows a positive correlation with EGR1 expression in human glioma tissues." (PMID 38398118, 2024). "METTL3-dependent m6A modification stabilizes HOTAIRM1 in glioma cells." (PMID 39691597, 2024). "Furthermore, the expression of METTL3 is positively correlated with higher glioma grades and poorer prognosis." (PMID 39473440, 2024). "METTL3 exhibits high expression in glioma and plays an oncogenic role." (PMID 38405130, 2024). "Western blot analysis also showed a significant up-regulation of METTL3 in glioma tissues." (PMID 38012763, 2023). "Furthermore, rescue assays were conducted to explore the regulatory function of HOTAIRM1/METTL3/IGFBP2 in glioma cell cellular processes and VM formation." (PMID 38012763, 2023). "Additionally, METTL3 promotes the suppressor of cytokine signaling 2 (SOCS2) degradation in gliomas by promoting an m6A methylation modification of SOCS2 to inhibit M1 macrophage polarization." (PMID 37759870, 2023). "In our study, we uncovered that METTL3 expression was high in glioma cells and tissues." (PMID 38012763, 2023). "In glioma cells, knockdown of METTL3 significantly reduced the expression of LINC01003." (PMID 37270527, 2023). "Similarly, the migratory and invaded glioma cell numbers significantly increased under METTL3 overexpression while showed reduced numbers under METTL3 silencing." (PMID 38012763, 2023). "Co-culture of monocyte and glioma cells demonstrated that glioma cells overexpressing METTL3 inhibited SOCS2 expression and M1 polarization of monocytes, while SOCS2 overexpression could rescue this inhibition." (PMID 37671161, 2023). "These conflicting views on the role of METTL3—whether it promotes or suppresses glioma—may be attributed to the diverse target genes affected by m6A and the heterogeneity of tumor stem cells, both genetically and non-genetically." (PMID 37964279, 2023). "In addition, immunohistochemical staining also presented similar results in glioma tissues, further confirming elevated levels of METTL3 in glioma cells and tissues." (PMID 38012763, 2023). "We found that METTL3 mediates the expression and m6A modification of LINC01003, suggesting that METTL3-mediated m6A modification may be responsible for the upregulation of LINC01003 in glioma." (PMID 37270527, 2023). "Notably, HOTAIRM1 silencing reversed the impact of METTL3 overexpression on glioma cell malignancy and VM formation." (PMID 38012763, 2023). "Additionally, METTL3 upregulates the expression of COL4A1 by reducing its methylation level to participate in glioma development." (PMID 37759870, 2023).
glioma (continued). "In addition, METTL3 promotes malignant growth in IDH wild-type gliomas via the mechanism of enhancing MALAT1 stability through m6A alteration with the aid of HuR and by means of activating NF-κB." (PMID 35937991, 2022). "Similarly, we showed that METTL3 overexpression annulled the promoting effect of circDLC1 silencing on glioma cell proliferation." (PMID 35474040, 2022). "Furthermore, METTL3 promotes the temozolomide (TMZ) resistance of glioma cells by increasing DNA repair genes O6-methylguanine-DNA methyltransferase (MGMT) and alkylpurine–DNA–N-glycosylase (ANPG)." (PMID 36008936, 2022). "METTL3, as an m6A modifying enzyme, is poorly expressed in glioma." (PMID 35474040, 2022). "Moreover, METTL3-silenced pancreatic cancer cells and glioma stem cells (GSCs) showed enhanced irradiation sensitivity." (PMID 35186927, 2022). "Furthermore, Chang and colleagues found that METTL3 was highly expressed in IDH wild-type gliomas, and the high expression of METTL3 was positively correlated with higher tumour malignancy and poor prognosis." (PMID 35688823, 2022). "METTL3 expression was positively correlated with circDLC1 expression in glioma tissues (p < 0.01)." (PMID 35474040, 2022). "METTL3 expression showed a positive correlation with circDLC1 in glioma tissues." (PMID 35474040, 2022). "The reduction of METTL3-mediated m6A modification results in the in vivo growth of glioma cells." (PMID 35474040, 2022). "Our results exhibited that METTL3 expression was reduced in glioma tissues and cells (p < 0.05)." (PMID 35474040, 2022). "Interestingly, METTL3 showed opposite prognostic value in gliomas of the RNA-seq and Microarray cohorts." (PMID 34246306, 2021). "However, the current study provides evidence that JMJD1C plays a tumor‐inhibiting role in glioma by upregulating miR‐302a and further affecting the METTL3/SOCS2‐mediated polarization of M1 macrophages." (PMID 34586733, 2021). "METTL3 could also impair the proliferation and mobility of glioma cells, indicating the dual role of METTL3 in GBM." (PMID 33879256, 2021). "Also, methyltransferase‐like 3 (METTL3) has been found to be upregulated in the tumorigenic glioma stem‐like cells, while suppressor of cytokine signaling 2 (SOCS2) exerts inhibitory effects on glioma." (PMID 34586733, 2021). "In this study, we demonstrated that METTL3 acts as a critical promoter of TMZ resistance in glioma." (PMID 34336690, 2021). "However, the exact functions of m6A ‘writers,’ ‘erasers,’ and ‘readers’ are still largely elusive in gliomas, such as both oncogenic and tumor suppressive roles of m6A writer METTL3 have been reported in GBM-derived stem cells (GSCs)." (PMID 34246306, 2021). "Furthermore, we investigated the effect of mRNA methylase METTL3 on SOCS2 expression in glioma cells." (PMID 34586733, 2021). "METTL3 has been shown previously to be essential for survival of glioma stem‐like cells." (PMID 34586733, 2021). "According to the TCGA, genetic amplifications at the METTL3 locus arise in ~ 1% of gliomas." (PMID 32375856, 2020). "Other studies showed that m6A writer METTL3 could promote chemo-/radio-resistance in pancreatic cancer cells and glioma stem-like cells." (PMID 32760220, 2020). "In contrast Visvanathan described a pro-oncogenic role of METTL3 in glioma stem cells." (PMID 33375621, 2020). "Similarly, METTL3 is overexpressed in gliomas and is involved in the maintenance of its radio-resistance." (PMID 33072775, 2020). "In glioma, METTL3 can promote glioma radioresistance and stem-like cell maintenance." (PMID 33015074, 2020). "In addition, several studies have shown that METTL3 mRNA and m6A levels are elevated in glioma compared to normal brain, therefore leading multiple researchers to investigate the effects of upregulating and suppressing METTL3 on glioma growth." (PMID 32375856, 2020).
glioma (continued). "Two other studies stated that either increased or decreased METTL3 expression could respectively promote the self-renewal and tumorigenicity of glioma stem-like cells." (PMID 31230592, 2019). "In addition, the notch pathway-dependent luciferase activity was induced in glioma cells upon exogenous overexpression of METTL3." (PMID 30781903, 2019). "Thus, the pathways involved in glioma stem cell maintenance and tumorigenesis are positively influenced by METTL3-mediated RNA stabilization implying an oncogenic role for METTL3 in GSCs." (PMID 30781903, 2019). "Consequently, SOX2 mediated the METTL3-dependent maintenance and radioresistance of glioma stem-like cells." (PMID 30149601, 2018). "Thus our study reports the importance of m6A modification in glioma stem cell growth and uncovers METTL3 as a potential molecular target in GBM therapy." (PMID 29460395, 2018). "We speculate whether METTL3 targets MIF through EIF3J-AS1 to inhibit autophagy in gliomas." (PMID 41390674, 2025). "Furthermore, METTL3 enhances the stability of SOX2 mRNA, protecting glioma stem-like cells from radiation cytotoxicity, and METTL3-induced stabilization of nuclear paraspeckle assembly transcript 1 (NEAT1) and the activation of the miR-3773p/Nampt axis confer neuroprotection in ischemic injury." (PMID 41294873, 2025). "Moreover, USP25 enhances EGFR expression through cytosolic METTL3, driving glioma progression." (PMID 41321637, 2025). "Consequently, caution is advised when considering METTL3 as a therapeutic target for glioma." (PMID 38398118, 2024). "Additionally, we used rescue assays to explore whether METTL3 was involved in HOTAIRM1-mediated glioma cell malignancy and VM formation." (PMID 38012763, 2023). "Furthermore, HuR was reported to be essential for METTL3-mediated stabilization of metastasis-associated lung adenocarcinoma transcript 1 (MALAT1), which subsequently activated nuclear factor kappa B (NFκB) in IDH-wildtype glioma." (PMID 35625706, 2022). "Finally, we verified the regulation of METTL3-mediated circDLC1 on glioma cells in vivo." (PMID 35474040, 2022). "The analysis of clinical glioma samples reveals a positive correlation between USP25 and METTL3 protein levels, with both significantly upregulated in high-grade glioma." (PMID 41321637, 2025). "A previous study demonstrated that METTL3 induces LINC00475 splicing in an m6A-dependent manner, enhancing mitochondrial fission and autophagy to drive glioma progression." (PMID 41390674, 2025). "As one of the substrates of METTL3, high expression of SRSF7 also significantly promotes the progression of glioma." (PMID 40469294, 2025). "In METTL3-overexpressing glioma cells, EIF3J-AS1 knockdown led to decreased p62 and increased LC3II expression, thereby reversing METTL3-mediated autophagy suppression." (PMID 41390674, 2025). "Analysis of TCGA transcriptome data revealed a significant positive correlation between METTL3 and EIF3J-AS1 expression in glioma tissues (P < 0.001, R2 = 0.02807)." (PMID 41390674, 2025). "The protein levels of both METTL3 and USP25 were higher in high-grade gliomas (WHO Grades III and IV) compared to low-grade gliomas and non-tumor brain samples." (PMID 41321637, 2025). "METTL3 also enhances MALAT1 stability through its interaction with RNA-binding protein HuR, leading to NF-κB activation and promoting IDH wild-type glioma progression." (PMID 41390674, 2025). "METTL3-mediated m6A modification stabilizes SOX2 mRNA, thereby maintaining the stemness properties of glioma stem cells (GSCs) and consequently driving radioresistance." (PMID 40823093, 2025). "METTL3 activates the Wnt/β-catenin signaling pathway by promoting m6A methylation of LINC00839, thereby maintaining glioma stem cell stemness and inducing radioresistance." (PMID 41390674, 2025).
glioma (continued). "Collectively, these findings suggest that METTL3 suppresses MIF expression through EIF3J-AS1, thereby inhibiting autophagy in glioma cells." (PMID 41390674, 2025). "Mechanistically, METTL3 induced the generation of LINC00475-S by splicing LINC00475 through m6A modification and subsequently promotes mitochondrial fission in glioma cells by inhibiting the expression of MIF." (PMID 38405130, 2024). "In glioma, EGR1 induced the methyltransferase METTL3 to promote the proliferation and self-renewal of CSCs." (PMID 38467631, 2024). "In glioma development, the involvement of HUR in METTL3-mediated m6A modification of the lncRNA MALAT1 has been observed, leading to increased MALAT1 transcript expression and the promotion of glioma development through the ERK/MARK pathway." (PMID 38649363, 2024). "In conclusion, our findings suggest that C5aR1 inhibits ferroptosis in GBM cells and promotes MettL3-dependent GPX4 expression through ERK1/2, thereby promoting glioma progression." (PMID 39368999, 2024). "The resistance of glioma cells to mTOR inhibitors is attributed to m6A methylation at IRES sites, enhancing the translation of oncogenes, a process disrupted by METTL3/14 knockout." (PMID 38474421, 2024). "A positive correlation between METTL3 and both LINC00475 and LINC00475-S was identified in glioma tissues." (PMID 38405130, 2024). "METTL3 facilitated HNRNPH1-mediated AS of LINC00475, which promoted glioma progression by inducing mitochondrial fission." (PMID 38405130, 2024). "Knockdown of the histone methyltransferase SETD2, which influences m6A modification, results in decreased levels of METTL3/14 and WTAP, reducing glioma cell proliferation and migration." (PMID 38474421, 2024). "The upregulation of METTL3 and FSP1 induced by fear stress increases the m6A level of glioma tumor tissue, providing a new understanding of glioma development by inhibiting the tumor progression caused by ferroptosis." (PMID 38550378, 2024). "In glioma endothelial cells, IGF2BP3, in combination with METTL3, stabilizes CPEB2, maintaining the blood–tumor barrier and thereby influencing drug delivery." (PMID 38474421, 2024). "In conclusion, METTL3-mediated m6A triggered mitochondrial fission by facilitating the binding between HNRNPH1 and LINC00475, thereby promoting glioma progression." (PMID 38405130, 2024). "miR-1208 targets METTL3’s 3′UTR region, diminishing NUP214 levels, and inhibiting glioma cell proliferation." (PMID 38474421, 2024). "METTL3-dependent m6A methylation enhanced the binding of GYR and GY domains of HNRNPH1 to LINC00475, ultimately promoting glioma progression by inducing mitochondrial fission." (PMID 38405130, 2024). "Under fear stress, increased METTL3 expression stabilizes FSP1 through m6A methylation and inhibits ferroptosis in glioma cells, indicating a role in stress responses." (PMID 38474421, 2024). "To elucidate the role of m6A modifiers in regulating AS of LINC00475, we initially assessed the expression levels of METTL3, ALKBH5, and FTO in glioma cells." (PMID 38405130, 2024). "Subsequently, overexpression experiments for METTL3, FTO, and ALKBH5 were conducted in glioma cells." (PMID 38405130, 2024). "The results in the report showed that high levels of METTL3 expression have been observed in glioma tissues compared to normal brain tissues, and METTLE3 expression informed worse survival of glioma patients." (PMID 38398118, 2024). "METTL3 downregulation has been shown to reduce the expression of stem cell-specific markers SSEA1, glioma reprogramming factors POU3F2, SOX2, SALL2, OLIG2, neurosphere formation, and the proportion of viable cells." (PMID 37522921, 2023). "For example, YTHDF2 promotes glioma malignancy by degrading UBXN1 mRNA, while METTL3-mediated m6A modification enhances glioma metastasis by stabilizing PCBP2." (PMID 38171932, 2023).